NRG1 (neuregulin 1)
Description:
Direct ligand for ERBB3 and ERBB4 tyrosine kinase receptors. Concomitantly recruits ERBB1 and ERBB2 coreceptors, resulting in ligand-stimulated tyrosine phosphorylation and activation of the ERBB receptors. The multiple isoforms perform diverse functions such as inducing growth and differentiation of epithelial, glial, neuronal, and skeletal muscle cells; inducing expression of acetylcholine receptor in synaptic vesicles during the formation of the neuromuscular junction; stimulating lobuloalveolar budding and milk production in the mammary gland and inducing differentiation of mammary tumor cells; stimulating Schwann cell proliferation; implication in the development of the myocardium such as trabeculation of the developing heart. Isoform 10 may play a role in motor and sensory neuron development. Binds to ERBB4. Binds to ERBB3. Acts as a ligand for integrins and binds (via EGF domain) to integrins ITGAV:ITGB3 or ITGA6:ITGB4. Its binding to integrins and subsequent ternary complex formation with integrins and ERRB3 are essential for NRG1-ERBB signaling. Induces the phosphorylation and activation of MAPK3/ERK1, MAPK1/ERK2 and AKT1. Ligand-dependent ERBB4 endocytosis is essential for the NRG1-mediated activation of these kinases in neurons (By similarity).
Synonyms: ARIA; HRG; GGF; HGL; HRGA; NDF; SMDF; GGF2; HRG1; MST131; MSTP131; NRG1-IT2
Tractability: Antibody: its Gene Ontology location is reachable by antibodies, with high confidence; UniProt places it where antibodies can reach, with medium confidence; UniProt predicts a signal peptide or a membrane-spanning region.
Gene: Protein-coding gene on chromosome 8 (31,639,222 to 32,855,666, forward strand). Ensembl gene ENSG00000157168.
Subcellular location: Cell membrane (Pro-neuregulin-1, membrane-bound isoform); Secreted (Neuregulin-1); Nucleus (Isoform 8); Secreted (Isoform 9); Membrane (Isoform 10)
Subcellular location (Human Protein Atlas): Nucleoplasm; Predicted to be secreted
Pathways (Reactome):
Signal Transduction: Downregulation of ERBB2 signaling; Downregulation of ERBB2:ERBB3 signaling; ERBB2 Activates PTK6 Signaling; ERBB2 Regulates Cell Motility; GRB2 events in ERBB2 signaling; GRB7 events in ERBB2 signaling; Nuclear signaling by ERBB4; PI3K events in ERBB2 signaling; PI3K events in ERBB4 signaling; PI5P, PP2A and IER3 Regulate PI3K/AKT Signaling; PIP3 activates AKT signaling; RAF/MAP kinase cascade; SHC1 events in ERBB2 signaling; SHC1 events in ERBB4 signaling; Signaling by ERBB2; Signaling by ERBB4
Disease: Constitutive Signaling by Aberrant PI3K in Cancer; Signaling by ERBB2 KD Mutants; Signaling by ERBB2 TMD/JMD mutants
Neuronal System: Long-term potentiation
Gene Ontology:
Molecular function: ErbB-3 class receptor binding; integrin binding; protein tyrosine kinase activator activity; receptor ligand activity; transcription coregulator activity; chemorepellent activity; cytokine activity; growth factor activity; receptor tyrosine kinase binding; transmembrane receptor protein tyrosine kinase activator activity; signaling receptor binding
Biological process: activation of protein kinase B activity; cardiac muscle cell myoblast differentiation; endocardial cell differentiation; ERBB signaling pathway; ERBB2-ERBB3 signaling pathway; ERBB2-ERBB4 signaling pathway; ERBB3 signaling pathway; ERBB4 signaling pathway; ERBB4-ERBB4 signaling pathway; negative regulation of DNA-templated transcription; negative regulation of secretion; positive regulation of cell population proliferation; positive regulation of ERK1 and ERK2 cascade; positive regulation of protein-containing complex assembly; regulation of postsynaptic neurotransmitter receptor internalization; ventricular trabecula myocardium morphogenesis; brain development; cardiac muscle cell differentiation; cell communication; cell differentiation; intracellular signal transduction; mammary gland development; nervous system development; neural crest cell development; peripheral nervous system development; and 6 more
Cellular component: extracellular region; glutamatergic synapse; membrane; nucleus; plasma membrane
Genetic constraint (gnomAD): Loss-of-function variants: 16 observed, 61.22 expected, observed/expected ratio (o/e) 0.26, 90% interval 0.18 to 0.4. The upper end of that interval is the gene's LOEUF score, 0.4, which puts it in group 1 of 6, group 1 being the genes least tolerant of losing a copy. Missense variants: 745 observed, 819.06 expected, observed/expected ratio (o/e) 0.91, 90% interval 0.86 to 0.97. Synonymous variants: 298 observed, 304.63 expected, observed/expected ratio (o/e) 0.98, 90% interval 0.89 to 1.08.
Homologues: Orthologues: chimpanzee NRG1 (93% identical), rabbit NRG1 (91% identical), dog NRG1 (89% identical), mouse Nrg1 (88% identical), rat Nrg1 (88% identical), macaque NRG1 (76% identical), guinea pig NRG1 (73% identical), pig NRG1 (72% identical), tropical clawed frog nrg1 (64% identical), zebrafish nrg1 (47% identical). Paralogues in human: NRG2 (37% identical), NRG3 (18% identical), NRG4 (5% identical).
Diseases named in the same sentence as NRG1 in open-access papers:
NRG1 is named in the same sentence as 313 diseases in open-access papers, as found by Europe PMC text mining. Sharing a sentence is not in itself a finding about the gene and the disease. The quoted sentences say what the papers report.
schizophrenia (344 papers, 2005 to 2026). A major psychotic disorder characterized by abnormalities in the perception or expression of reality. "One potential point of convergence between interneuron dysfunction, myelination abnormalities, and schizophrenia risk involves the NRG1–ErbB4 signaling pathway." (PMID 40410588, 2025). "Functionally, NRG1 expression, in the presence of cannabis, acts as an anxiolysis and is associated with Schizophrenia by disinhibiting the dopamine secreting substantia nigra neurons, effecting their adulthood firing rates." (PMID 39109071, 2024). "The current study examined the relation between the genetic polymorphisms of COMT rs4680, NRG1 rs35753505, NRG1 rs3924999, and treatment response to risperidone in patients with psychosis from the schizophrenia spectrum." (PMID 39062492, 2024). "Numerous studies have identified the neuregulin 1 (NRG1) gene as a risk factor for the development of schizophrenia in various populations." (PMID 38918041, 2024). "Another important mechanism explaining the complex role of neuregulin 1 in cognitive functions of schizophrenia spectrum patients relies on its risk C-alleles, which were associated with the expression of NMDA receptors with a negative impact on cognition." (PMID 39518545, 2024). "Germline mutations in NRG1 are associated with developmental brain disorders such as schizophrenia as well as degenerative disorders such as amyotrophic lateral sclerosis and Alzheimer’s disease." (PMID 39210279, 2024). "NRG1 is a developmental regulator that has long been implicated in the pathobiology of schizophrenia." (PMID 39334950, 2024). "Many studies have indicated that the neuromodulin 1 (NRG1) and ErbB4 genes, the susceptibility genes of mental illness, are linked with the bipolar disorder and schizophrenia susceptibility genes." (PMID 38291418, 2024). "Although the schizophrenia risk gene NRG1 is known to affect the wiring of inhibitory interneurons, its role in excitatory neurons and axonal development is unclear." (PMID 38918041, 2024). "We and others have previously shown that the schizophrenia risk gene Nrg1 is expressed in excitatory pyramidal neurons, whereas its specific receptor Erbb4 is mainly found in inhibitory interneurons." (PMID 38918041, 2024). "This study shows that the schizophrenia risk gene NRG1 controls the development of callosal connections and implicates NRG1 signaling in the regulation of GAP43, a key protein for axonal growth." (PMID 38918041, 2024). "Here we show that a schizophrenia (SCZ)-associated mutation in Nrg1 disrupts its ability to communicate extracellular signals to the neuronal genome that results in altered expression of a gene network enriched for orthologs of SCZ-susceptibility genes." (PMID 39214704, 2024). "In so doing, they link the effects of olanzapine and NRG-1 deficiency-induced mitochondrial dysfunction to an NRG-1/miRNA-143-3p nexus that is associated with developmental pathobiology in schizophrenia and clinical response to antipsychotic drugs." (PMID 39334950, 2024). "Not only NRG1, but also its receptors, ErbB2 and ErbB4 are candidate susceptibility genes for schizophrenia." (PMID 37251644, 2023). "Neuregulin 1 (Nrg1) encodes a tropic factor and is genetically linked with several neuropsychiatry diseases such as schizophrenia, bipolar disorder and depression." (PMID 37147705, 2023). "This cascade is clinically relevant since disruption of Nrg1-ErbB4 signaling is associated with epilepsy, intellectual disability and schizophrenia." (PMID 37779671, 2023). "We used adult male mice in this study, as the schizophrenia-relevant phenotype of Nrg1 mutants, as well as their susceptibility to cannabinoids is not as pronounced in female mice of this line." (PMID 37233814, 2023). "Like other genes and receptors are considered as the candidate risk genes for schizophrenia, both NRG1 and ErbB4 receptor have also been reported." (PMID 36692676, 2023).
schizophrenia (continued). "Multiple studies have suggested that the neuregulin-1 gene (NRG1) serves as an important risk gene for schizophrenia that is thought to be characterized by deficits in glutamatergic neurotransmission." (PMID 37251644, 2023). "Subsequently, evidence from studies of mouse models has demonstrated that overexpression of heterozygous NRG1 type III in mice regulates schizophrenia-relevant behaviors, indicating that NRG1 is associated with abnormal behavioral phenotypes in schizophrenia." (PMID 35337293, 2022). "Two other schizophrenia susceptibility genes are NRG1 and ERBB4, which are part of the “signaling by ERBB4” and “long-term potentiation” pathway together with DLG4." (PMID 36561312, 2022). "Neuregulin (NRG) is an NTF closely related to the development of the central nervous system and comprises NRG1-4 isoforms, among which NRG1 and its receptor ErbB4 are thought to be among the susceptibility genes for schizophrenia." (PMID 35337293, 2022). "Neuregulin 1 (NRG1) is a well-established genetic risk factor for schizophrenia, and a mutation in the transmembrane domain region of NRG1 is found in patients with schizophrenia." (PMID 36406747, 2022). "Recent meta-analyses provided support for the association of NRG1 with schizophrenia, although with a variety of haplotypes located throughout the gene (Li, Collier, & He, 2006; Munafò, Thiselton, Clark, & Flint, 2006; Tosato, Dazzan, & Collier, 2005)." (PMID 36168994, 2022). "Neuregulin-1 (NRG1), encoded by the schizophrenia candidate gene NRG1, binds to its receptors, ErbB4, and activates the receptors." (PMID 35680847, 2022). "The NRG1-ErbB4 pathway has been implicated in early schizophrenia association studies and rare structural variants in the ERBB4 gene have been identified in ASD, however, these results have not been replicated." (PMID 36224258, 2022). "Among these candidates, genes encoding the proteins neuregulin (Nrg1) and its receptor ErbB4 have been shown to be promising susceptibility genes of schizophrenia." (PMID 35562880, 2022). "This study indicates that mPFC NRG1 upregulation is one of the main causes of FGR-induced schizophrenia, which leads to significant reduction of PV interneuron number in mPFC." (PMID 36460658, 2022). "Genetic studies in humans have implicated the gene encoding neuregulin-1 (NRG-1) as a candidate susceptibility gene for schizophrenia." (PMID 36620856, 2022). "Research of knockouts of the Neuregulin-1 (NRG1)gene which has been identified as a candidate susceptibilitygene for schizophrenia, revealed a selective impairment inresponse to social novelty in NRG1 mutants, but not in sociability." (PMID 35733816, 2022). "NRG1 generates many kinds of isoforms, several of which have been associated with schizophrenia-like behavior in animal model study." (PMID 36590092, 2022). "Genes encoding NRG1 and its predominant receptor on neuron, ErbB4 both confer risk of schizophrenia." (PMID 36590092, 2022). "The impairments in brain morphology and physiology induced by mutations in NRG1–ErbB4 signaling correlate very well with the changes observed in people diagnosed with schizophrenia." (PMID 35682647, 2022). "BACE1 cleavage of NRG1 regulates myelination, and increased BACE1 cleavage of NRG1 has been implicated in the development of schizophrenia." (PMID 35119166, 2022). "There are consistent reports of reduced expression of genes (MAG, MAL, MBP, PLP, MOG, NRG1, and Olig2, among others) associated with oligodendrocytes and myelin, and therefore involved in neuronal development or signal transmission in schizophrenia." (PMID 35326310, 2022). "Genes encoding the NRG1 protein and its receptor epidermal growth factor receptor 4 (ErbB4) are implicated in schizophrenia pathogenesis." (PMID 35682647, 2022).
schizophrenia (continued). "In this study, we found that the leading cause of FGR-induced schizophrenia was the significant upregulation of NRG1 in mPFC, which impaired PV interneuron GABAergic maturation and resulted in subsequent schizophrenia behaviors in mice." (PMID 36460658, 2022). "The NRG1 gene encoding Neuregulin-1 located on chromosome 8p is associated with a risk of schizophrenia." (PMID 34502372, 2021). "NRG1 is one of the 108 schizophrenia-associated identified genes and is significantly associated with endophenotypes of schizophrenia via regulating myelination, neuronal migration, and function of neurotransmitter receptors." (PMID 34055795, 2021). "Neonatal treatment with EGF and neuregulin 1 (NRG1) produced long-lasting behavioral impairments implicated in schizophrenia-like symptoms." (PMID 34072341, 2021). "NRG1, which controls the formation of excitatory and inhibitory synapses in cortical circuits, is a schizophrenia risk gene, and is associated with multiple relapsing disorders." (PMID 34347624, 2021). "Neuregulin 1 (NRG1) is a critical growth factor during brain development, and the NRG1 gene has been identified as a potential susceptibility gene for some mental disorders, such as schizophrenia or BD." (PMID 33144710, 2021). "The schizophrenia-associated susceptibility factors that interact closely with NMDARs like neuregulin 1 (NRG1) and its receptor ErbB4, both main genetic risk factors associated with schizophrenia." (PMID 34899420, 2021). "The NRG1 has been originally reported to be associated with schizophrenia and has been implicated in neuro developmental processes including neuronal differentiation and synapse formation." (PMID 33897409, 2021). "In patients with schizophrenia, LIM Kinase (LIMK) was also found to be deregulated, and a direct molecular link was established between LIMK and neuregulin 1, which is encoded by a schizophrenia-susceptibility gene." (PMID 33790791, 2021). "The neuregulin 1 (NRG1) ErbB4 module is at the core of an “at risk” signaling pathway in schizophrenia." (PMID 33871014, 2021). "Human genetic studies have shown that variants of the NRG1 gene increase the risk of psychiatric diseases including schizophrenia, but results are still debated." (PMID 32690068, 2020). "Alteration of NRG1 expression or genetic polymorphism in Nrg1 gene are linked to the pathophysiology of schizophrenia." (PMID 31838721, 2020). "Natural genetic variants of Neuregulin1 (NRG1) and its cognate receptor ErbB4 are associated with a risk for schizophrenia." (PMID 32354758, 2020). "Cortical white matter abnormalities have been described in bipolar disorders and schizophrenia, and have been associated with an abnormal expression of neuregulin-1, which plays a crucial role in oligodendrocyte development and function." (PMID 32676012, 2020). "Disruption of normal NRG/ERBB signaling has been implicated in impaired brain functioning and a number of psychiatric disorders, with the NRG1 gene most notably implicated in schizophrenia." (PMID 32228684, 2020). "Similar results were also obtained by three meta-analysis studies examining the association between NRG1 and schizophrenia." (PMID 31649580, 2019). "The schizophrenia risk gene NRG1 controls the formation of excitatory and inhibitory synapses in cortical circuits." (PMID 31583038, 2019). "Of the 11 schizophrenia risk variants, only NRG1 rs6994992 has been previously examined for its association with creativity (Kéri, 2010)." (PMID 31649580, 2019). "Both NRG1 and ErbB4 receptor have been identified as candidate risk genes for schizophrenia through genetic studies." (PMID 31417356, 2019). "Neuregulin 1 (NRG1) is essential for the development of the nervous system and the heart and its deregulation has been linked to cancer, schizophrenia and bipolar disorder (BPD) (OMIM# 181500)." (PMID 31767031, 2019).